EGFR (epidermal growth factor receptor)
Diseases named in the same sentence as EGFR in open-access papers (continued):
Sharing a sentence is not in itself a finding about the gene and the disease.
lung adenocarcinoma (continued). "Integrin β1 was expressed in all molecular subtypes of lung adenocarcinoma, though expression was lower in EGFR-mutated tumors (n = 17, mean 1.4 ± SD 0.7) relative to KRAS-mutated tumors (n = 40, mean 1.9 ± SD 0.8, P = 0.03) and all other tumors (n = 8, mean 2.1 ± SD 0.5, P = 0.04) (data not shown)." (PMID 35763345, 2022). "This study aimed to access the predictive value of inflammatory indices and clinical factors in toxicity and survival in patients with epidermal growth factor receptor (EGFR)-mutated lung adenocarcinoma receiving first-line tyrosine kinase inhibitor (TKI)-treatment." (PMID 35330404, 2022). "MET amplification may lead to secondary resistance to EGFR-TKIs in patients with EGFR-mutated lung adenocarcinoma." (PMID 35402233, 2022). "However, optimal methods of extracting information about EGFR mutation from pGGN lung adenocarcinoma images remain uncertain." (PMID 36119545, 2022). "However, in this case, we reported a lung adenocarcinoma patient carrying D761Y mutation present before EGFR-TKI treatment." (PMID 35866776, 2022). "A patient with EGFR L858R lung adenocarcinoma developed disease progression after 72.7 months of gefitinib therapy; rebiopsy was done, and next-generation sequencing showed the disappearance of the previous EGFR mutations." (PMID 36387181, 2022). "Moreover, we revealed that lung adenocarcinoma patients with positive 7-AABs test had a higher ratio of EGFR mutation and worse pathologic features." (PMID 36531072, 2022). "The risk-scoring model may be clinically helpful in tailoring treatment strategies in patients with advanced EGFR-mutated lung adenocarcinoma." (PMID 35053473, 2022). "In addition, the presence of EGFR mutations and the single nucleotide polymorphism (SNP) of Aurora kinase A is associated with earlier tumor stage of the lung adenocarcinoma." (PMID 36011604, 2022). "The prognostic factors for RFS after complete resection of primary lung adenocarcinoma based on EGFR mutation status remain unclear." (PMID 36085020, 2022). "These non-invasive, quantitative and convenient methods to predict the EGFR mutation in spinal metastases may help guide individualised treatment in lung adenocarcinoma." (PMID 36011018, 2022). "In Asians, ~50% of lung adenocarcinomas harbor epidermal growth factor receptor (EGFR) mutations." (PMID 35069906, 2022). "EGFR was also identified as associated with lung adenocarcinoma in the GWAS Catalog." (PMID 35681244, 2022). "For instance, approximately 61% lung adenocarcinoma patients in China have an EGFR mutation." (PMID 35230491, 2022). "Therefore, existing guidelines recommend genetic testing for lung adenocarcinoma patients before treatment, such as EGFR mutations and anaplastic lymphoma kinase (ALK) fusion mutations." (PMID 35692818, 2022). "Four (30%) studies were focused on whether radiomics could predict epidermal growth factor receptor (EGFR) mutation in spinal metastases of primary lung adenocarcinoma." (PMID 35162902, 2022). "Platelets in high D-dimer plasma may be activated and implicated in acquired resistance to EGFR TKI in advanced lung adenocarcinoma with mutant EGFR." (PMID 35756605, 2022). "Among Iranian patients with lung adenocarcinoma, 19.8% harbored EGFR gene mutation." (PMID 35463723, 2022). "Given that EGFR-sensitive mutations account for more than half of lung adenocarcinomas, we next investigated whether SIRT6 is also involved in the TKI resistance mechanism associated with poor prognosis in these patients." (PMID 35915188, 2022). "The activation of this pathway is an additional mechanism that could lead to TKI resistance in EGFR-mutated lung adenocarcinomas and merits in-depth investigation also considering its therapeutic implications." (PMID 35456982, 2022). "Furthermore, the FGA isoform has been shown to be a predictor of targeted therapy in patients with EGFR-mutated lung adenocarcinoma." (PMID 35463955, 2022).
lung adenocarcinoma (continued). "Moreover, we looked at the effect of exosomes derived from EGFR-mutated lung adenocarcinoma on epithelial cells." (PMID 35954442, 2022). "EGFR is one of the most common driver gene mutations of lung adenocarcinoma." (PMID 36248982, 2022). "Here we conducted this study to explore whether EGFR-TKIs combined with chemotherapy would benefit advanced lung adenocarcinoma patients with both sensitive EGFR mutation and concomitant non-EGFR genetic alterations." (PMID 36172729, 2022). "We observed 65 cases of lung adenocarcinoma with EGFR mutations, of which 56 (86%) could be identified using the Idylla EGFR cartridge if used." (PMID 35627184, 2022). "Therefore, extraction of EGFR mutation information from lung adenocarcinoma manifesting as pGGN on images remains uncertain." (PMID 36119545, 2022). "Hence, we reported that a patient with advanced lung adenocarcinoma harboring the EGFR T263P mutation, L858R mutation and MET amplification was resistant to osimertinib but significantly benefited from erlotinib and capmatinib treatment." (PMID 36212397, 2022). "The prevalence and impact of epidermal growth factor receptor (EGFR) Q787Q polymorphism on the treatment of lung adenocarcinoma remains unclear." (PMID 35387120, 2022). "Asian patients with lung adenocarcinoma are more likely to have EGFR mutations." (PMID 36233811, 2022). "Furthermore, LMR, NLR, and mutation types can be used as independent prognostic markers of survival in patients diagnosed with lung adenocarcinoma harboring EGFR mutations receiving TKIs." (PMID 35330404, 2022). "In summary, we identified a new EGFR exon 21 indel mutation in a patient with lung adenocarcinoma." (PMID 36042660, 2022). "Its inhibition was shown to re-sensitise human and murine lung adenocarcinoma resistant to gefitinib, as well as human cell lines harbouring the osimertinib driver resistant mutation EGFR C797S, via the inhibition of HES1 protein by the binding of phospho-STAT3 to its promoter." (PMID 35681591, 2022). "Mutations of EGFR leading to its overexpression have been associated with lung adenocarcinoma." (PMID 35328664, 2022). "Thus, we developed and validated a CT-based deep learning model with clinical factors for predicting EGFR mutation status in lung adenocarcinoma manifesting as pGGN." (PMID 36119545, 2022). "The activation of SHP2 by mutated EGFR is crucial for EGFR mutation driven lung adenocarcinoma." (PMID 35061863, 2022). "Mei Dongdong analyzed CT images of lung adenocarcinoma and explored whether cell characteristics could become a substitute biomarker for EGFR mutation." (PMID 36685887, 2022). "EGFR-mutated lung adenocarcinoma patients who received tyrosine kinase inhibitors (TKIs) may initially respond to therapy, but over time, resistance eventually occurs." (PMID 35268520, 2022). "Osimertinib can exert stronger growth inhibitory effects in NSCLC patients with a high expression of EphB4 than in those with a low expression of EphB4, and it may improve the prognosis in EGFR mutation-positive lung adenocarcinoma patients." (PMID 34445227, 2021). "In May 2014, the Taiwan Nation Health Insurance Bureau permitted both 30 mg and 40 mg afatinib daily as a first-line therapy for advanced lung adenocarcinoma with susceptible EGFR mutations." (PMID 33941115, 2021). "In addition, the results of the FLAURA study have also demonstrated that osimertinib provides a better prognosis than gefitinib and erlotinib as a first-line treatment for patients with EGFR mutation-positive lung adenocarcinoma." (PMID 34445227, 2021). "In addition, expression of this mutation is known to promote Erlotinib resistance in EGFR-mutant lung adenocarcinoma cells." (PMID 33801659, 2021). "It is still unclear whether epidermal growth factor receptor (EGFR) mutation of primary lung adenocarcinoma can be detected on sputum samples." (PMID 33757469, 2021).
lung adenocarcinoma (continued). "The clinical utility of using a single gene-based biomarker as a therapeutic focus for lung adenocarcinoma was first realized with the discovery of mutations in the tyrosine kinase domain of EGFR in 2004; this enabled the identification of patients with greater sensitivity to TKIs." (PMID 34367939, 2021). "Regarding the mutations we found in our patients collective, targeted therapy has been used with success in adenocarcinoma of the lung with EGFR mutations, PIK3 inhibitors in stage four melanoma or MEK inhibitors in inoperable plexiform neurofibromas with NF1 mutations." (PMID 34065301, 2021). "In lung adenocarcinoma, mutation status of EV-associated DNA from pleural effusion correlated with cfDNA, while presence of mutated EGFR informed about the EGFR tyrosine kinase inhibitor treatment efficacy." (PMID 33995103, 2021). "These activating gene mutations for the EGFR are present in 10–20% of lung adenocarcinomas." (PMID 33435596, 2021). "The addition of β-blockers was noted to improve progression-free survival in patients with lung adenocarcinoma with EGFR mutations receiving afatinib compared to patients taking afatinib without any β-blockers, as observed in a reanalysis of a phase III clinical trial." (PMID 34094953, 2021). "And then, it was reported that Six loci, represented by seven SNPs (rs2736100 at 5p15.33, rs2853677 at 5p15.33, rs2179920 at 6p21.32, rs3817963 at 6p21.3, rs7636839 at 3q28, rs7216064 at 17q24.3, and rs2495239 at 6p21.1) have been associated with the risk of lung adenocarcinomas with EGFR mutation." (PMID 33707471, 2021). "This study aims to compare the prevalence of EGFR mutation status in bronchoalveolar lavage samples with the prevalence in peripheral blood, referring to the gold standard—tissue biopsy, in patients with primary lung adenocarcinoma." (PMID 34040898, 2021). "Furthermore, we observed that rs73569323 carrying at least T genotype (CT and TT) allele was significant associated with tumor status of lung adenocarcinoma patients with EGFR L858R mutation (OR = 3.886, 95% CI = 1.000–15.103, p = 0.039)." (PMID 34948746, 2021). "First, given that NGS was not performed for all patients, specifically excluding some patients with EGFR mutations who were initially identified by conventional PCR, there could be a potential bias in investigating the mutation profile in lung adenocarcinoma." (PMID 33960703, 2021). "Therefore, this study aimed to investigate the prognostic factors in patients with BM from EGFR mutation-positive lung adenocarcinoma, including the effect of denosumab." (PMID 34577890, 2021). "Hence, the purpose of this work is the evaluation of polycaprolactone electrospun (PCL-ES) scaffolds for culturing LCSCs in sensitive and resistant EGFR-mutated (EGFRm) lung adenocarcinoma cell models." (PMID 34771484, 2021). "Similarly, resistance to tyrosine kinase inhibitors (TKIs) in hepatocellular carcinoma and EGFR mutation-positive lung adenocarcinomas was counteracted by PHGDH knockdown." (PMID 33397437, 2021). "All 6 patients had lung adenocarcinoma harboring EGFR mutations." (PMID 33863951, 2021). "In addition, the incidence of pleural invasion was higher, and the incidence of EGFR mutation in STAS+ lung adenocarcinoma was lower than that in STAS− adenocarcinoma." (PMID 34249691, 2021). "Therefore, it is an important unmet need to identify patients at high risk for recurrence in resected early stage EGFR-mutated lung adenocarcinoma." (PMID 34298845, 2021). "The TRU-type is a lung adenocarcinoma with bronchial epithelial phenotype with initial oncogene mutations such as EGFR, KRAS, and MET amplification, HER2 amplification, and later a second mutation leading to the loss of the BRM protein causing a subsequent poorer differentiation of the tumor." (PMID 34440689, 2021).
lung adenocarcinoma (continued). "Clinical trials are currently underway to assess the efficacy of novel molecular‐targeted drugs or immune checkpoint inhibitors in EGFR‐mutated lung adenocarcinoma patients with T790M‐negative or with an unknown mutation." (PMID 33586356, 2021). "Epidermal growth factor receptor (EGFR) mutations are major drivers of oncogenic alterations that account for an important molecular subtype of lung adenocarcinoma, comprising 40–60% of cases in the South-East Asian population and 10–20% among Caucasian patients." (PMID 34663810, 2021). "In addition, WWOX rs3764340 and rs73569323 polymorphisms are highly correlated with the size of the primary tumor and the invasion of adjacent tissues in Taiwanese lung adenocarcinoma patients carrying the EGFR-L858R mutation gene." (PMID 34948746, 2021). "However, because of the advantages of targeted therapy in perfect disease control and disease-free survival in lung adenocarcinoma, many guidelines still recommend TKIs as the first-line treatment in EGFR mutated NSCLC." (PMID 33549061, 2021). "The result also concurred with the hypothesis for the progression of lung adenocarcinoma that EGFR-mutated AAH follows a linear progression schema, whereby AAH progresses to AIS and is followed by MIA." (PMID 35096585, 2021). "The risk of a negative influence on quality of life (QoL) and OS, caused by SREs, could be significant in patients with EGFR-mutated lung adenocarcinoma and bone metastases." (PMID 34201833, 2021). "This is particularly pronounced for EGFR-mutated lung adenocarcinomas." (PMID 35052732, 2021). "The short in-frame deletions of exon 19 (Exon19 in-frame deletion) mutation and the single-point substitution of leucine by arginine at codon 858 (L858R) mutation are located in the tyrosine kinase domain and account for approximately 90% of all EGFR mutations in lung adenocarcinoma." (PMID 34948746, 2021). "We identified, for the first time, an epigenomic factor that can potentially complement DNA mutation status in discriminating patients with lung adenocarcinoma who are less likely to benefit from EGFR-TKI treatment, thereby leading to improved patient management in precision medicine." (PMID 34036228, 2021). "All patients had lung adenocarcinoma and EGFR-sensitive mutation." (PMID 35046801, 2021). "EGFR-dependent pathways of EGFR-TKIs, including gefitinib, erlotinib, and osimertinib, have been well studied, and common mechanisms between them that exert antitumor effects in EGFR mutation-positive lung adenocarcinoma have been demonstrated." (PMID 34445227, 2021). "Lung adenocarcinomas with MLCs tend to appear as a solid mass on CT and harbor EGFR gene mutations." (PMID 34234879, 2021). "Somatic mutations were identified using WES of tumor and germ line DNA; as expected, EGFR-mutant lung adenocarcinoma patient NCI-RA007 had much fewer somatic mutations compared with the melanoma patient–derived cell lines, NCI-3784Mel and NCI-3795Mel (2678 and 2031, respectively)." (PMID 34391887, 2021). "It has been shown that 10–30% of all lung adenocarcinomas contain an EGFR-activating mutation." (PMID 33435596, 2021). "Here, we report a case of EGFR-mutated lung adenocarcinoma with cervical metastasis." (PMID 34505336, 2021). "Results from several other studies also supported that radiomic features from the contrast-enhanced CT scan showed superiority over the unenhanced CT phase in lung adenocarcinoma diagnosis, differentiating lung adenocarcinoma from squamous cell carcinoma and EGFR-related mutation prediction." (PMID 34660285, 2021). "Previous studies have found that cigarette smoking dosage over 30 pack-years was an independent negative predictive factor and meanwhile smoking cessation combined with anti-EGFR treatment like erlotinib seems to be more effective in lung adenocarcinoma with EGFR mutation." (PMID 34322390, 2021).
lung adenocarcinoma (continued). "Despite the presence of podoplanin-expressing CAFs and a relatively poor response to EGFR TKIs among patients with lung adenocarcinoma harboring EGFR-activating mutations, the molecular mechanism remains unclear." (PMID 33673405, 2021). "Moreover, the EGFR-mutated biopsy samples from the advanced lung adenocarcinoma had a higher frequency of micropapillary pattern than EGFR-wild type tumors." (PMID 34975346, 2021). "It has been confirmed that an increase in CEA levels during TKI treatment for EGFR mutation patients may be a more sensitive predictor of an explosive progression in lung adenocarcinoma." (PMID 34391435, 2021). "We earlier reported a distinct frequency of 23% EGFR mutations and 18% KRAS mutations in lung adenocarcinoma patients of Indian ethnicity compared to 10–15% vs. 27–62% EGFR mutations and 25–50% vs. 5–15% KRAS mutations among the Caucasians and East Asians populations." (PMID 33796225, 2021). "The date of EGFR-mutated advanced lung adenocarcinoma diagnosis was referred as index date." (PMID 34434112, 2021). "Finally, the recent implementation of EGFR TKIs in multimodality treatment of locally advanced EGFR-mutated lung adenocarcinoma represents a new precision medicine approach which promises to improve outcomes in these patients." (PMID 34202748, 2021). "The specimen of the lesion over the right clavicle disclosed a microscopical picture of metastatic carcinoma with tumor cells immunohistochemically positive for TTF-1 and negative for p40, which was compatible with the results of stains of primary EGFR-mutated lung adenocarcinoma." (PMID 33640029, 2021). "The association between ER expression and clinico-pathological parameters such as EGFR gene mutation may elucidate the prognostic role of ER expression in lung adenocarcinoma." (PMID 35008242, 2021). "Notably, the lung adenocarcinoma patients with a high TSHZ2 expression tended to have EGFR mutations less frequently and a preferable prognosis to those with a lower expression." (PMID 33850468, 2021). "These treatment options should be explored within clinical trials in the future and may further improve the outcome of patients with advanced EGFR-mutated lung adenocarcinoma." (PMID 33919291, 2021). "As the most common driver mutation in lung adenocarcinoma, EGFR mutation could predict response to the EGFR tyrosine kinase inhibitors (TKIs)." (PMID 34026636, 2021). "We aimed to investigate the feasibility of detecting epidermal growth factor receptor (EGFR) mutations in cell-free DNA (cfDNA) from cerebrospinal fluid (CSF) and plasma of advanced lung adenocarcinoma (LADC) with brain metastases (BMs) by droplet digital polymerase chain reaction (ddPCR)." (PMID 33828979, 2021). "Furthermore, our results indicate that shallow whole-genome plasma sequencing in EGFR-mutated lung adenocarcinoma patients provides clinically relevant information." (PMID 33919291, 2021). "Conversely, in lung adenocarcinoma cells harbouring an EGFR mutation, DDX3X overexpression induces a CSC-like phenotype (increased Sox2 and Snail expression and elevated anchorage-independent proliferation) and resistance to EGFR-tyrosine kinase inhibitors (EGFR-TKIs)." (PMID 33627125, 2021). "In lung adenocarcinoma, a strong association between the ERs and EGFR mutations has been reported." (PMID 35008242, 2021). "Interestingly, approximately 10–35% of patients with lung adenocarcinoma harbor tumor-associated EGFR mutations." (PMID 34876693, 2021). "As we know, EGFR mutations were very common in these subtypes of lung adenocarcinomas." (PMID 34234879, 2021). "In this study, the EGFR gene mutation rate was higher than usual for cases of lung adenocarcinoma." (PMID 33550544, 2021). "Especially in Asian lung adenocarcinoma patients, the frequency of EGFR mutations is higher." (PMID 34868228, 2021).